EMSY (EMSY transcriptional repressor, BRCA2 interacting)
Description:
Regulator which is able to repress transcription, possibly via its interaction with a multiprotein chromatin remodeling complex that modifies the chromatin. Its interaction with BRCA2 suggests that it may play a central role in the DNA repair function of BRCA2. Mediates ligand-dependent transcriptional activation by nuclear hormone receptors.
Synonyms: C11orf30; GL002
Tractability: PROTAC: ubiquitination databases record sites on it; its protein half-life has been measured.
Gene: Protein-coding gene on chromosome 11 (76,444,887 to 76,553,031, forward strand). Ensembl gene ENSG00000158636.
Subcellular location: Nucleus
Subcellular location (Human Protein Atlas): Nucleoplasm; Centrosome
Gene Ontology:
Molecular function: protein binding; identical protein binding
Biological process: regulation of DNA-templated transcription
Cellular component: nucleoplasm; nucleus
Genetic constraint (gnomAD): Loss-of-function variants: 25 observed, 133.23 expected, observed/expected ratio (o/e) 0.19, 90% interval 0.14 to 0.26. The upper end of that interval is the gene's LOEUF score, 0.26, which puts it in group 1 of 6, group 1 being the genes least tolerant of losing a copy. Missense variants: 1,291 observed, 1,648.7 expected, observed/expected ratio (o/e) 0.78, 90% interval 0.75 to 0.82. Synonymous variants: 569 observed, 589.59 expected, observed/expected ratio (o/e) 0.97, 90% interval 0.9 to 1.03.
Homologues: Orthologues: chimpanzee EMSY (100% identical), macaque EMSY (99% identical), pig EMSY (98% identical), rabbit EMSY (98% identical), guinea pig EMSY (98% identical), rat Emsy (94% identical), mouse Emsy (90% identical), tropical clawed frog emsy (74% identical), zebrafish emsy (56% identical), Drosophila melanogaster CG15356 (19% identical).
Diseases named in the same sentence as EMSY in open-access papers:
EMSY is named in the same sentence as 19 diseases in open-access papers, as found by Europe PMC text mining. Sharing a sentence is not in itself a finding about the gene and the disease. The quoted sentences say what the papers report.
asthma (11 papers, 2015 to 2025). "Our observations suggest that CDHR3 and EMSY may play important roles in the pathogenesis of asthma in Chinese individuals." (PMID 33213402, 2020).
breast carcinoma (8 papers, 2005 to 2025). "Given the convergence of four breast-cancer-associated genes (EMSY, ETS-1, KDM5B, and miR-31) with overlapping biological roles, this pathway offers a number of avenues for therapeutic intervention." (PMID 24582497, 2014). "We focused our investigation on the plant homeodomain (PHD)-containing protein PF1 (PHF12), which links SIN3 PAH2 to a chromatin-modifying protein complex containing MRG15, LID (the Drosophila homolog of KDM5A/B) and EMSY that has been implicated in breast cancer." (PMID 26460951, 2015). "The EMSY (c11orf30) gene maps to 11q13-11q14, a locus that harbors several known and potential oncogenic drivers frequently amplified in breast cancer, most notably in the estrogen-receptor-positive (ER+) luminal subtype." (PMID 24582497, 2014). "EMSY, a putative oncogene involved in gene regulation, is known to be amplified in approximately 13% of sporadic breast cancers." (PMID 25927669, 2014). "This pathway represents one mechanism by which EMSY exerts its oncogenic and metastatic potential in breast cancer, resulting in a poor outcome prognosis of EMSY-amplified breast tumors." (PMID 24582497, 2014). "EMSY is amplified in 12% of breast cancers and 17% of high-grade ovarian cancers and its amplification has been associated with an increased risk of relapse as well as decreased survival in breast cancer patients." (PMID 16029503, 2005). "Altogether, our results identify EMSY as a regulator of miRNA gene expression and provide insights into the molecular mechanisms by which EMSY contributes to the initiation or progression of breast cancer." (PMID 24582497, 2014). "Viré and colleagues have elegantly documented a novel role for EMSY in breast cancer." (PMID 25927669, 2014).
ovarian carcinoma (6 papers, 2005 to 2023). A malignant neoplasm originating from the surface ovarian epithelium. "EMSY (C11orf30) is a novel gene that could be involved in low-level predisposition to breast and ovarian cancer." (PMID 16029503, 2005). "EMSY is a transcriptional repressor that associates with BRCA2 and is often amplified in breast and ovarian cancers." (PMID 29720118, 2018). "Previous studies have identified an amplification on chromosome 11 in 18% of ovarian cancers, and have proposed that the target gene of this event is EMSY (C11ORF30)." (PMID 20844748, 2010).
Fanconi anemia (2 papers, 2019 to 2020). Fanconi anemia (FA) is a hereditary DNA repair disorder characterized by progressive pancytopenia with bone marrow failure, variable congenital malformations and predisposition to develop hematological or solid tumors. "Other defects in homologous recombination repair genes, such as EMSY, RAD51, ATM, ATR, Fanconi anemia, BARD1, BRIP1, PALB2, RB1, NF1, CDKN2A, and the suppression of BRCA1 transcriptional activation through gene methylation, are associated with homologous recombination deficiency (HRD)." (PMID 32679669, 2020).
colorectal cancer (1 paper, 2018). A primary or metastatic malignant neoplasm that affects the colon or rectum. "We further narrowed this list by filtering genes with a known role in human colorectal cancer and/or cellular response to ionizing radiation that resulted in a group of four genes -CAB39, EMSY, EREG, and MEX3C." (PMID 29720118, 2018). "Finally, analysis of a TCGA colorectal cancer dataset revealed that CAB39 and EMSY are upregulated at the protein level in a significant number of CRC patients." (PMID 29720118, 2018).
cutaneous melanoma (1 paper, 2024). A primary melanoma arising from atypical melanocytes in the skin. "Only EMSY was recurrently affected by BA-SVs in both cutaneous and mucosal melanomas, and only CDKN2A and CDKN2B were recurrently affected by BA-SVs in both acral and cutaneous melanomas." (PMID 38758740, 2024).
tumor (5 papers, 2016 to 2022). "Conversely, one tumor pair shared missense mutations in three genes (EMSY, SMAD4, and POM121L12) and gene copy number amplification of three genes (SDHA, TERT, and EGFR)." (PMID 33139840, 2020). "miR-653-5p was identified to target different genes, such as EMSY, and RAI14, which participate in many tumor developments." (PMID 34983591, 2022). "miR-31 also regulates the expression of several target-suppressive or oncogenic genes, such as ARID1A, SATB2, EMSY, and ABCB9, to affect tumorigenesis and tumor progression and prognosis." (PMID 27793031, 2016).
cancer (3 papers, 2010 to 2022). A tumor composed of atypical neoplastic, often pleomorphic cells that invade other tissues. "Considering all these discrepancies, the role of EMSY in DNA repair and cancer therapy still remains unclear and requires further investigation." (PMID 29707144, 2018).
EMSY also shares sentences with these, for which no sentence is quoted: allergic rhinitis (3 papers); eczema (2); allergic disease (1); atopic dermatitis (1); breast tumors (1); Crohn disease (1); dermatitis (1); food allergy (1); melanoma (1); mucosal (1); pituitary tumor (1).